SIRT3 (sirtuin 3)
Diseases named in the same sentence as SIRT3 in open-access papers (continued):
Sharing a sentence is not in itself a finding about the gene and the disease.
ischemia (23 papers, 2016 to 2024). A hypoperfusion of the BLOOD through an organ or tissue caused by a PATHOLOGIC CONSTRICTION or obstruction of its BLOOD VESSELS, or an absence of BLOOD CIRCULATION. "For example, the protective role of silent information regulation 2 homolog 3 (SIRT3) in ischemia-induced neuronal death as well as the underlying mechanisms was studied in PC-12 cells." (PMID 30579328, 2018). "Although the loss of SIRT1/SIRT3 led to a compromised PGC‐1α/PPARα‐mediated transcriptional control of fatty acid oxidation in response to acute ischemia and I/R, their crosstalk in mitochondria plays a more important role in the aging heart during acute ischemia." (PMID 37537789, 2023). "Herein we believed SIRT1 works as an adaptive protection in aging during acute ischemia by increasing its mitochondria distribution and bonding to more SIRT3." (PMID 37537789, 2023). "Our results showed that SIRT3 expression decreased with reperfusion time following spinal cord ischemia; however, RIPC performed before ischemia increased SIRT3 expression and rescued SIRT3 downregulation induced by I/R." (PMID 36927808, 2023). "Resveratrol can reduce intestinal ischemia-reperfusion injury by activating the SIRT3/FoxO3a pathway, increasing the expression of SOD2 and catalase, reducing ROS and LPO production, compensating for the GSH/GPX4 pathway and inhibiting ferroptosis." (PMID 37858064, 2023). "The compromised SIRT3 activity and decreased mitochondria SIRT1–SIRT3 interaction led to aging hearts being more sensitive to acute ischemia." (PMID 37537789, 2023). "The present study investigated the altered distribution of short‐form SIRT1 and SIRT3 in young and aged hearts during acute ischemia and long‐term I/R stress." (PMID 37537789, 2023). "Several investigators have reported that SIRT3 expression in mouse hippocampal neurons is decreased after acute ischemic stroke and that acute ischemia-induced neuronal damage is attenuated under conditions of SIRT3 overexpression." (PMID 36374406, 2023). "In aged hearts, SIRT1 translocated into mitochondria and recruited more mitochondria SIRT3 to enhance their interaction during acute ischemia, acting as adaptive protection for the aging hearts from further mitochondria dysfunction." (PMID 37537789, 2023). "We then detected their expression, acetylation, and their interaction with SIRT3 in response to acute ischemia and I/R stress in the heart." (PMID 37537789, 2023). "We found that the induction of longevity-promoting SIRT3 was important for the protective effects against ischemia injury of clinical drugs including Clo, Asp and NBP." (PMID 36012382, 2022). "Omentin1 maintained mitochondrial dynamical homeostasis and promoted PINK1/Parkin-dependent mitophagy via SIRT3/FOXO3a signaling, thereby improving MI-induced HF and enhancing the resistance of myocardium to prolonged ischemia injury." (PMID 36192726, 2022). "In an ischemia animal model, SIRT3 expression was found to be increased in macrophages, and increased SIRT3 promoted microglial N9 cells migration by upregulating CX3CR1." (PMID 36111151, 2022). "Given the critical role of mitochondria in ischemia, SIRT3 is able to exert ischemia-protecting effects through its direct modulation of mitochondrial function, such as ROS detoxification and tricarboxylic acid cycle." (PMID 36012382, 2022). "In an ischemia research, SIRT3 SUMOylation triggered by SENP1 subsequently results in increased levels of COX1, SOD2, and IDH2 protein acetylation, which caused oxidative stress and mitochondrial dysfunction in vitro and in vivo." (PMID 36111151, 2022). "We concluded that ANXA1sp promotes expression and activity of SIRT3 in mitochondria of kidney tubules following I/R, which likely helps to improve mitochondrial function following ischemia." (PMID 34276404, 2021).
ischemia (continued). "A more recent study reported that 3-hydroxybutyrate infusion in ischemia induced by transient middle cerebral artery occlusion in mice, reduced infarct size, mediated by sirtuin 3, increased complex I activity in the mitochondria, and reduced ROS production." (PMID 29489818, 2018). "A growing body of evidence has confirmed that SIRT3 defends against oxidative stress in multiple diseases including ischemia and neurodegenerative disease." (PMID 28003866, 2016). "To determine the effects of the SIRT1‐SIRT3 interaction on cardiac metabolic homeostasis under physiological and pathological conditions, we performed the SIRT3‐target proteomics analysis of the whole left ventricle under sham operation, acute ischemia, and I/R stress conditions." (PMID 37537789, 2023). "Ischemic stress can increase the PDHE1α‐SIRT3 interaction as an adaptive response in the young acute ischemia group, while this interaction was higher in the aged sham and I/R group except for acute ischemia condition versus the young group, respectively." (PMID 37537789, 2023). "This adaptive response could maintain the stability of the SIRT1–SIRT3 complex in aged mitochondria during acute ischemia, which could be a protection for SIRT3 and its mediated mitochondria regulation." (PMID 37537789, 2023). "Thus, SIRT1 plays a role in modulating SIRT3‐mediated mitochondrial function and substrate metabolism to adapt to myocardial acute ischemia and I/R stress." (PMID 37537789, 2023). "In view of the important role of endothelial cells in microvascular circulations, we hypothesized that the endothelial expression of the longevity gene SIRT3 may be protective in ischemia-like models." (PMID 36012382, 2022). "Furthermore, we will investigate to what extent SIRT3 can protect mitochondrion and how SIRT3 exerts the modulation of mitochondrial function in ischemia-like injury." (PMID 36012382, 2022). "More importantly, using an in vitro ischemia model, we demonstrated that downregulation of Sirt3 could aggravate the oxygen‐glucose deprivation‐induced BBB disruption and apoptosis." (PMID 33421349, 2021). "The cytoprotective effects of DHM in a variety of pathologic conditions including non-alcoholic fatty liver disease (NAFLD), osteoarthritis, cardiac ischemia/reperfusion injury, and hypobaric hypoxia-induced memory impairment involve the modulation of SIRT3 expression and/or activity." (PMID 32850822, 2020). "In vivo, WT or SIRT3 global knockout (KO) mice were exposed to right upper and lower limbs RIPC or sham ischemia." (PMID 36927808, 2023). "We further examined the effects of cardiomyocyte SIRT1 and SIRT3 deletion on the mitochondrial structure of the AAR in hearts' left ventricles under sham operation, acute ischemia, and I/R stress." (PMID 37537789, 2023). "Peroxisome proliferator-activated receptor-gamma coactivator 1 α (PGC-1α) is reported to positively regulate the expression of SIRT3 in DCM, ischemia-induced oxidative stress and mitochondrial biogenesis." (PMID 36671063, 2023). "Inhibition of the mPTP does not improve recovery of cardiac function after ischemia in both WT and SIRT3-/- hearts although it significantly reduces ROS production and LDH release in the coronary effluent from SIRT3-/- mice." (PMID 28559847, 2017). "However, we did not observe any changes in the protein level of SIRT3 at the end of ischemia or at the end of reperfusion." (PMID 38216627, 2024). "However, the hyperacetylation of PDHE1α and PDHE1α‐SIRT3 interaction was not significantly altered between SIRT1f/f and icSIRT1−/− hearts during both sham, acute ischemia and I/R conditions." (PMID 37537789, 2023). "Interestingly, previous studies and our data suggest that the compensatory mechanisms developed in SIRT3-/- mice protect the heart against mild but not severe ischemia." (PMID 28559847, 2017).
colon carcinoma (22 papers, 2014 to 2025). "Some studies focused on colon cancer have demonstrated that SIRT3 was highly expressed in colorectal cancer and was associated with its tumor stage and lymph node metastasis." (PMID 40421455, 2025). "Overall, our data suggests that enhanced SIRT3 expression is associated with colon carcinoma growth and spread among a cohort of Chinese colon cancer patients." (PMID 25105144, 2014). "In univariate Cox regression analysis, SIRT3 expression pattern was significantly associated with the colon cancer-specific mortality (hazard ratio (HR) 2.68; 95% confidence interval (CI), 1.48–4.28, P = 0.0015)." (PMID 25105144, 2014). "Moreover, reversing the dysregulated metabolism of glucose and fatty acid in colon cancer by dihydrotanshinone I (DHTS) has been shown to be linked to lower levels of SIRT3 gene expression within a metabolic reprogramming occurring through the PTEN/AKT/RHEB/MTOR/HIF1α signal pathway." (PMID 34360883, 2021). "SIRT3 was shown to impair tumor growth by inhibiting glycolysis and cell proliferation or by promoting apoptosis in breast, lung, and colon cancer." (PMID 41391757, 2025). "In contrast, it SIRT3 was suggested to promote the development of acute myeloid leukemia, diffuse large B cell lymphoma, breast, lung, and colon cancer with various genetic backgrounds." (PMID 41391757, 2025). "GAD is the main active component of Ganoderma lucidum, and GAD inhibits the energy metabolism reprogramming of colon cancer cells by activating SIRT3 to induce deacetylation of CypD." (PMID 35832551, 2022). "Clinical observations indicated that in colon cancer patients, the survival rate was 64.6% among patients with high SIRT3 expressions and 88.6% among patients with low SIRT3 expressions (log-rank P = 0.016)." (PMID 34360883, 2021). "In this study, we detected the SIRT3 expression in tumor samples from colon cancer patients and analyzed its correlation to clinical outcomes in those patients." (PMID 25105144, 2014). "The colon cancer-specific survival was 64.6% among patients with high SIRT3 expressions and 88.6% among patients with low SIRT3 expressions (log-rank P = 0.016)." (PMID 25105144, 2014). "Pertinence of this study is to address the role of SIRT3 in colon cancer and to explore its potential application in colon cancer treatment." (PMID 25105144, 2014). "Our data showed that the colon cancer-specific survival rate was 64.6% among patients with high SIRT3 expressions and 88.6% among patients with low SIRT3 expressions (log-rank P = 0.016)." (PMID 25105144, 2014). "Patients with low SIRT3 expression had improved five-year colon cancer-specific survival and overall survival compared to patients with high SIRT3 expression determined by the IRS score." (PMID 25105144, 2014). "SIRT3 facilitates chemoresistance in colon cancer cells by regulating SOD2 and PGC-1α." (PMID 35571098, 2022). "A recent study has shown that whey could target SIRT3 expression to induce metabolic dysfunctions and modulate the bioenergy characteristics of colon cancer cells." (PMID 35832551, 2022). "Higher SIRT3 expression might shorten the colon cancer-specific survival and the overall survival of patients." (PMID 35571098, 2022). "Moreover, in line with previous studies, our data indicated the role of SIRT3 as a key player in the control of the mitochondrial function in colon cancer cells." (PMID 34360883, 2021). "In vitro studies showed that silencing SIRT3 in colon cancer cells resulted in an increase in oxidative burden, changes of the mitochondrial biogenesis, inhibition of cell proliferation and increased activation of apoptosis, thus consequently sensitizing cells to cytotoxic treatments." (PMID 34360883, 2021). "This means that the ES of SIRT3 functions as a tumor suppressor in colon cancer." (PMID 32962686, 2020). "It was reported that SIRT3 silencing could be a therapeutic strategy to render colon cancer cells more sensitive to treatment." (PMID 32962686, 2020).
colon carcinoma (continued). "Silencing of SIRT3 was shown to impair mitochondrial biogenesis in colon cancer cells." (PMID 33273545, 2020). "Furthermore, SHMT2-K95-Ac was increased in SIRT3 knockout colon cancer cells, and this outcome was also confirmed in cells in which SIRT3 was stably knocked down." (PMID 30367038, 2018). "Treatment targeting the SIRT3 protein may be alternative or adjunctive to current chemotherapy for colon cancer patients." (PMID 25105144, 2014). "The mechanisms of SIRT3 promoting tumor cell survival may be due to both decreased apoptosis and increased cell proliferation, both of which are hallmarks of colon cancer carcinogenesis." (PMID 25105144, 2014). "Further study of SIRT3 in a larger population as well as in different ethnical groups is warranted in order to better understand prognostic and therapeutic values of SIRT3 as a biomarker in colon cancer." (PMID 25105144, 2014). "Therefore, protein therapy targeting SIRT3 may be used as a complementary or alternative strategy to existing colon cancer chemotherapy." (PMID 40241794, 2025). "In addition, SIRT3 has been demonstrated to be an independent prognostic factor in colon cancer." (PMID 35571098, 2022). "Surprisingly, the correlation of SIRT3 expression and human colon cancer remains unknown." (PMID 25105144, 2014). "To confirm the successful induction of the 6 model genes (SIRT3, PIK3CA, ITGA3, DAPK1, PAK1, and CASP3), we gathered a set of 39 colon cancer tissue samples." (PMID 38213716, 2024). "Taken together, these results suggest that PROX1 can recruit EZH2 to the SIRT3 promoter region in colon cancer cells, where EZH2 represses SIRT3 transcription." (PMID 36594098, 2023). "Therefore, SIRT3 may be a therapeutic and novel target for inhibiting colon cancer." (PMID 35571098, 2022). "On the other hand, knockdown of SIRT3 reversed NOS1-induced apoptosis resistance of SW480 and SW620 colon cancer cells." (PMID 34360883, 2021). "Sirt3 KO mice contained a significantly decreased number of colon tumors, and the expression level of SHMT2 was dramatically lower in Sirt3 KO cancer cells." (PMID 30367038, 2018). "For instance, mitochondrial neuronal nitric oxide synthase (nNOS, NOS1) could increase SIRT3 activity and thereby activating SOD2 to regulate ROS production properly, thus, suppressing apoptosis of colon cancer cells." (PMID 35832551, 2022). "Reduction in tumor size and delay in tumor growth by rATRAM-GRA8-M/AS was dependent on PKCα, SIRT3, ATP5A1, and the acetylation status of ATPA1 K506 and K531 in the HCT116 colon-cancer xenograft model." (PMID 32002124, 2020). "Although molecular mechanisms of SIRT3 in carcinogenesis are not completely clear, this finding encourages further study on SIRT3-based treatment in colon cancer." (PMID 25105144, 2014). "SIRT3 has been confirmed to enhance chemotherapy resistance of colon cancer by modulating the acetylation of superoxide dismutase 2 (SOD2) and peroxisome proliferator-activated receptor-gamma co-activator-1alpha (PGC-1α), which enabled SIRT3 to be an independent prognostic factor for colon cancer." (PMID 40421455, 2025).
gastric cancer (22 papers, 2014 to 2025). A primary or metastatic malignant neoplasm involving the stomach. "SIRT3 is associated with enhanced gastric cancer risk and can thus be a potential prognostic marker." (PMID 35723384, 2021). "The results suggested that SIRT4, SIRT6, and SIRT7 were associated with Lauren classification and SIRT3-5 were associated with pStage in gastric cancer." (PMID 29088792, 2017). "In conclusion, although SIRT3 is well characterized in mitochondrial homeostasis against cell aging and transformation, expression of SIRT3 in tumor cells is linked with enhanced proliferation and aggressive growth of gastric cancer cells." (PMID 26121691, 2015). "To characterize the molecular signature of SIRT3-LDHA mediated bioenergetics in gastric cancer cells, we measured the expression of genes associated with glucose transportation and glycolysis." (PMID 26121691, 2015). "This study provides the evidence indicating that SIRT3 expressed in some cancer cells, such as gastric cancer cells, may be linked with the enhanced aggressiveness by SIRT3-mediated bioenergetics via deacetylation and activation of LADH." (PMID 26121691, 2015). "SIRT3, involved in mitochondrial metabolic homeostasis in gastric cancer, is considered a cancer-promoting factor." (PMID 35571098, 2022). "It was reported that downregulation of Notch-1 by SIRT3 inhibits the proliferation of gastric cancer cells." (PMID 35571098, 2022). "On the contrary, miR-708-5p and miR-421 inhibit the process of pancreatic ductal adenocarcinoma and gastric cancer by targeting SIRT3 to ablate the stimulatory activity on cell viability, invasion, and migration." (PMID 35832551, 2022). "The results indicated that 4-BR reduced human gastric cancer cell chemoresistance, suggesting that 4-BR increases chemosensitivity by inhibiting stemness and the SIRT3-JNK pathway." (PMID 35723384, 2021). "We evaluated the stemness inhibition ability of the SIRT3 inhibitor 4′-bromo-resveratrol (4-BR), an analog of resveratrol in human gastric cancer cells." (PMID 35723384, 2021). "We postulated that 4-BR would use the SIRT3-mediated pathway to downregulate gastric cancer stemness and increase chemosensitivity." (PMID 35723384, 2021). "By deacetylating and activating lactate dehydrogenase, SIRT3 facilitates anaerobic glycolysis and carcinogenesis in gastric cancer cells." (PMID 31817470, 2019). "We also confirmed that the gain of function of SIRT3 can recover the metabolic change in H. pylori infected gastric cancer cells." (PMID 29108235, 2017). "This study demonstrated that the expression of SIRT3 was elevated in a group of gastric cancer cells compared to normal gastric epithelial cells." (PMID 26121691, 2015). "Overexpression of SIRT3 increased cell growth, while SIRT3 knockdown inhibited cell growth of both gastric cancer cell lines." (PMID 26121691, 2015). "In this study, we investigated the potential role of SIRT3 in gastric cancer cells that express SIRT3." (PMID 26121691, 2015). "We found that SIRT3 protein levels were elevated in all 4 gastric cancer cell lines compared to the immortalized gastric epithelial GES-1 cells (AGS, 1.9-fold; SGC-7901, 1.5-fold; MGC-803, 2.0-fold; and HGC-27, 1.8-fold compared to GES-1 cells)." (PMID 26121691, 2015). "The multivariate analysis reported that SIRT3 could be an independent biomarker for the prediction of gastric cancer prognosis." (PMID 35571098, 2022). "Tenovin-6, a micromolar SIRT3 inhibitor, has anti-tumor ability in melanoma and gastric cancer cells, but its inhibitory effect remains unclear." (PMID 35832551, 2022). "Targeting the mitochondrial protein SIRT3 may provide a novel therapeutic option for gastric cancer treatment." (PMID 35723384, 2021).